Y_RNA (Y RNA )
Gene: Miscellaneous RNA gene on chromosome 4 (127,028,107 to 127,028,219, reverse strand). Ensembl gene ENSG00000199862.
Homologues: Orthologues: chimpanzee Y_RNA (98% identical), guinea pig Y_RNA (81% identical). Paralogues in human: RNY1 (81% identical), Y_RNA (81% identical), Y_RNA (80% identical), Y_RNA (79% identical), RNY1P11 (78% identical), Y_RNA (78% identical), Y_RNA (77% identical), RNY1P7 (76% identical), RNY1P8 (76% identical), Y_RNA (76% identical), Y_RNA (75% identical), RNY1P10 (74% identical), and 92 more.